CDKN1B (cyclin dependent kinase inhibitor 1B)
Diseases named in the same sentence as CDKN1B in open-access papers (continued):
Sharing a sentence is not in itself a finding about the gene and the disease.
breast cancer (continued). "The observation of monoallelic inactivation of the CDKN1B gene alteration in several tumors, including si-NET, breast cancers, and parathyroid adenomas, suggests that CDKN1B might be considered a haploinsufficient tumor suppressor." (PMID 39936980, 2025). "We evaluated the significance and predictive role of CDKN1B expression in breast cancer prognosis." (PMID 38248731, 2023). "CDKN1B may serve as an important biomarker in the treatment of breast cancer, and further experimental research and clinical trials of targeted drugs for CDKN1B may be necessary to clarify its clinical significance." (PMID 38248731, 2023). "The precise molecular mechanisms and pathways responsible for carcinogenesis in breast cancer, as determined by CDKN1B expression, remain unclear." (PMID 38248731, 2023). "According to our results, CDKN1B may represent a meaningful biomarker for breast cancer immunotherapy." (PMID 38248731, 2023). "CDKN1B expression plays a significant role in breast cancer progression, implying that targeting CDKN1B might be a promising strategy for treating breast cancer." (PMID 38248731, 2023). "In addition, functional relationships between CDKN1B and carcinogenesis of leukemia, breast cancer, colorectal cancer and other cancers have also been examined in many articles." (PMID 37432583, 2023). "In GSEA, low CDKN1B expression was associated with genes upregulated in the normal subtype of breast cancer, genes upregulated by mTOR kinase inhibitors, the T-cell receptor signaling pathway, and genes downregulated in memory CD8 T cells." (PMID 38248731, 2023). "Taken together, we provide evidence that LINC00355 functions by binding to the MENIN protein, which decreases its occupancy at the promoter of CDKN1B, decreasing protein levels of p27Kip, increasing proliferation, and cellular invasion in late-stage relapse breast cancer models." (PMID 35418131, 2022). "CDKN1B mutations have been associated with a wide variety of endocrine and non-endocrine neoplasms such as luminal breast cancer, prostate cancer, and hairy cell leukemia." (PMID 35355569, 2022). "Recently, it has been demonstrated that a subset of periarteriolar MSCs with a neuronal glial antigen 2 (NG2)+, Nestin+ phenotype produce TGF-β2 and BMP-7 to activate a quiescence pathway in metastatic breast cancer cells by inducing cyclin-dependent kinase inhibitor 1B (CDKN1B) via MAPK activation." (PMID 34831167, 2021). "In addition, inhibition of the ERBB2 pathway with a neutralizing antibody or small-molecule inhibitor for ERBB2 normalizes CDKN1B expression, leading to cell cycle arrest in human breast cancer cells." (PMID 33585479, 2021). "Furthermore, miR-575 expression was found to be upregulated in ER+ breast cancer cell with acquired tamoxifen resistance, whereas depletion of miR-575 partially re-sensitized these cells to tamoxifen by regulation of CDKN1B." (PMID 32929377, 2020). "Furthermore, ER+ breast cancer patients with higher CDKN1B expression levels have improved overall survival when receiving adjuvant tamoxifen therapy." (PMID 32929377, 2020). "Therefore, our results reveal that the miR-575- CDKN1B feedback loop is involved in tamoxifen sensitivity in ER+ breast cancer." (PMID 32929377, 2020). "In addition, at this age, the Cdkn1b-/- mammary glands show luminal ectasia (dilated milk ducts), a phenotype previously observed in BN rats resistant to E2-induced mammary tumors." (PMID 30893315, 2019). "A combination of three proteins comprising the receptors EGFR, ERBB3/HER3, and the cyclin-dependent kinase inhibitor p27 (CDKN1B) was found to be a potential biomarker for dependence on PI3K/AKT vs. MAPK/ERK signaling for drug resistance in HER2 breast cancers." (PMID 35582587, 2019).
breast cancer (continued). "We observed that only one of these 74 molecules (CDKN1B) is significantly mutated in breast cancers, and that 50 of them are not differentially expressed at mRNA level in tumors (all together or at subtype-level) when compared to non-tumor control samples." (PMID 29861861, 2018). "Moreover, expression of higher levels of quiescence and dormancy-associated genes, including CDKN1B and CHEK1, was observed in highly metastatic breast cancer cells considered to be tumor-initiating cells (TICs) with stem-like properties." (PMID 27845900, 2017). "Consistent with molecular profiles of the cell lines, in all 10 indications with significant numbers of HER2+ samples, EGFR expression was relatively higher and/or ERBB3 and CDKN1B lower in in comparison to breast cancers, and these patterns hold for both the HER2+ and HER2- subsets." (PMID 27035903, 2016). "However, SomInaClust also prioritized driver genes that are less frequently mutated in breast cancer like AKT1 (20 out of 772 mutations) and CDKN1B (7 mutations, representing less than 1% of all mutations across samples)." (PMID 25903787, 2015). "They found that the CDKN1B C -79T heterozygotes, but not the homozygotes, had a significantly increased risk of breast cancer." (PMID 22928041, 2012). "In addition to estrogen signaling and resistance to therapy, 7 of the identified genes have been previously associated with cell cycle regulation (CCND1, CDKN1A, CDKN1B, and CDKN2A) and breast cancer aggressiveness (CLDN7 and DLC1)." (PMID 22616718, 2012). "CDKN1B may also have implications for therapeutic strategies in breast cancer." (PMID 38248731, 2023). "Therefore, exosomal miR-455-5p in breast cancer cells may trigger the malignant phenotype of recipient cells via regulating CDKN1B gene; however, the interaction of miR-455-5p and CDKN1B has not been reported previously and needs further confirmation." (PMID 31763681, 2020). "In addition, our study also showed exosomal miR-455-5p in breast cancer cells may influence the phenotype of neighboring or distant non-malignant recipient cells by decreasing the expression of CDKN1B gene." (PMID 31763681, 2020). "We confirmed two tumor suppressor genes, suppressor of cytokine signaling 1 (SOCS1) and cyclin-dependent kinase inhibit 1B (CDKN1B), are negatively regulated in expression by both miR-221 and miR-222, which may have potential to be therapeutic targets for basal-like breast cancer treatment." (PMID 24886939, 2014). "The protein encoded by CDKN1B is found to bind to and prevent the activation of cyclin E-CDK2 or cyclin D-CDK4 complexes, therefore controls the cell cycle progression at G1 and its polymorphism appears to be an important predictive factor for breast cancer risk." (PMID 25034939, 2014). "To note, CDKN1B is now considered a driver gene for SI-NET, along with a specific subset of breast cancer defined as hormone receptor-positive (HR+) or luminal breast cancer (LBC)." (PMID 39936980, 2025). "In breast cancer, upregulation of SHCBP1 correlates with suppression of CDKN1A (p21) and CDKN1B (p27), which are crucial inhibitors of CDK activity." (PMID 41009347, 2025). "STAT6 was found to be a novel target of PVT1-derived miR-1207-5p, and miR-1207-5p promoted breast cancer cell growth by targeting STAT6, which in turn control CDKN1A and CDKN1B, confirming the tumor suppressing role of STAT6 in breast cancer." (PMID 28422733, 2017).
breast cancer (continued). "It has been shown that miR-221 and miR-222 functionally target and inhibit the expression of tumor suppressor genes (such as CDKN1B/p27 and CDKN1C/p57) and oncogenes (such as BCL2L1 and ER) in various cancers, including glioblastoma, hepatocellular carcinoma, breast cancer, and PCa." (PMID 37370750, 2023). "This study investigated the potential effects of CDKN1B, a negative cell cycle regulator, in breast cancer." (PMID 38248731, 2023). "To test this hypothesis, we knocked out CDKN1B in CCND1 amplified (MDA-MB-415) and CCND1 neutral (T47D) breast cancer cell lines." (PMID 35523804, 2022). "Moreover, we found that both CDKN1B and BRCA1 are targets of miR-575 and regulate miR-575-induced tamoxifen resistance in ER+ breast cancer." (PMID 32929377, 2020). "A total of 1180 miRNA–mRNA matched samples of breast cancer (including 1176 cancer and 104 normal tissues) were collected from the TCGA and the expression levels of crucial DEMs (miR-1255a and miR-455) and their target genes (SMAD4 and CDKN1B) were calculated." (PMID 31763681, 2020). "Our results predict that MAPK pathway-activating mutations (such as KRASG12V) may be genetic mechanisms of resistance to HER2-direted therapy in indications outside of breast cancer, with higher EGFR and lower ERBB3 and CDKN1B expression." (PMID 27035903, 2016). "Four known biomarkers (CHEK2 in both plasma and urine, CDKN1B, PCNA, and THBS1) were identified as false positives (red) in our breast cancer list, and seven (KRAS, GDNF in both breastmilk and plasma, MYCL1 in both blood and serum, CD40LG, CGA, CTAG1A, ERCC6, and HRAS) in our lung cancer list." (PMID 25379168, 2014). "Sporadic tumors (including breast cancer, prostate cancer, neuroendocrine tumors, and others) occurring as single tumors in the absence of any other findings of MEN4 frequently contain a somatic pathogenic variant in CDKN1B that is not present in the germline." (PMID 39194755, 2024). "Moreover, as determined by RT-qPCR, miR-575 expression exhibited a significant negative correlation with CDKN1B expression in ER+ breast cancer specimens but not in ER- breast cancer specimens." (PMID 32929377, 2020).
prostate carcinoma (95 papers, 1999 to 2025). A carcinoma that arises from epithelial cells of the prostate gland. "Several germline or somatic CDKN1B (the p27Kip1 encoding gene) mutations have been demonstrated to be associated with multiple endocrine neoplasia type 4 (MEN4), hairy cell leukemia, small-intestine neuroendocrine tumors, and breast and prostate cancers." (PMID 39936980, 2025). "Several lines of evidence from clinical and experimental studies demonstrate that there is a linkage between the chromosomal location of the CDKN1B gene (12p13) and prostate cancer susceptibility in a considerable number of FPC." (PMID 30065701, 2018). "The presence of a hemizygous deletion of the CDKN1B gene in human hematopoietic malignancies, ovarian and prostate cancers, associated with a reduced expression of P27 is indicative of a CDKN1B haploinsufficient behavior in those tumors." (PMID 25416039, 2015). "For example, loss of cyclin-dependent kinase inhibitor 1B (CDKN1B) has been described in 23% of prostate cancers." (PMID 25412927, 2014). "Furthermore, double IF staining with menin and CDKN1B antibodies showed that the reduced expression of CDKN1B in prostate carcinomas correlated well with the loss of menin expression, indicating that CDKN1B expression is indeed down-regulated in menin-negative prostatic cells." (PMID 20663219, 2010). "In vitro studies have shown that milk-derived miR-148 increased prostate cancer proliferation by inhibiting cyclin-dependent kinase inhibitor 1B (CDKN1B) and promoted DNA methyltransferase 1 (DNMT1)-dependent epithelial-mesenchymal transition (EMT)." (PMID 38201989, 2024). "The CCNB/CDK/cyclin dependent kinase inhibitor 1B pathway was confirmed to be related to cell cycle progression in prostate cancer." (PMID 35246013, 2022). "Consistent with previous study that suggested miR-150 negatively and post-transcriptionally regulated CDKN1B in prostate cancer stem cells, here we consolidated this regulatory axis in cervical carcinoma which was subjected to MIAT competition as well." (PMID 32549789, 2020). "Prostate cancer (PC), luminal breast cancer (LBC), and small intestine neuroendocrine tumors (SI-NET) are the cancer subtypes in which CDKN1B mutations have been identified as driver genetic lesions in a significant percentage of cases." (PMID 30065701, 2018). "These PIN lesions do not progress to metastatic cancer, whereas mice with both Pten+/− and Cdkn1b−/− develop prostate carcinoma with high penetrance." (PMID 29426892, 2018). "Germline CDKN1B pathogenic variants have been described in hereditary tumors, such as multiple endocrine neoplasia (MEN)-like syndromes and familial prostate cancer." (PMID 30065701, 2018). "Binding of melatonin to the MT1 receptor has been reported to up-regulate cyklin dependent kinase inhibitor gene (CDKN1B/p27) in prostate cancer." (PMID 27736994, 2016). "In mice, concomitant inactivation of Pten and Cdkn1b accelerates spontaneous neoplastic transformation of prostate cancer." (PMID 27366593, 2015). "Dual labeling fluorescence in situ hybridization using probes for 12p13 (CDKN1B; p27) and centromere 12 as a reference was used to successfully analyze more than 3700 prostate cancers with clinical follow-up data assembled in a tissue microarray format." (PMID 26293672, 2015). "Deletions of chromosome 12p11-13 (corresponding to CDKN1B(p27/Kip1I0)) have been identified in advanced human prostate cancer suggesting a tumor suppressor role for p27(Kip1)." (PMID 22454635, 2012). "This indeed correlates with the downregulation of CDKN1B observed in prostate carcinomas developed in our Men1 mutant mice." (PMID 20663219, 2010). "CDKN1B, which is closely related to the tumorigenesis of prostate cancers is among the transcriptional targets of menin." (PMID 20663219, 2010).
prostate carcinoma (continued). "We therefore analysed the expression of CDKN1B using IHC in serial sections of prostate carcinomas from Men1+/- mice." (PMID 20663219, 2010). "In addition, the experiments showed that the down-regulation of MBNL1-AS1 promotes the malignance of prostate cancer cell lines through the miR-221-3p/CDKN1B/C-myc axis by stimulating the stemness of tumor stem cells." (PMID 36497267, 2022). "Also, when Pten−/+ was coupled with Cdkn1b−/− (aka p27Kip1−/−), prostate carcinoma developed within 3 months of birth, with complete penetrance." (PMID 29426892, 2018). "Thus, these consolidated observations underscore a downstream role for PLK1, C-MYC and CDKN1B in SUB1-mediated prostate cancer cell proliferation and invasion." (PMID 27270442, 2016). "CDKN1B (p27): It is an important tumor suppressor gene in prostate cancer." (PMID 24282788, 2013). "Furthermore, our data showed that the expression of the cyclin-dependent kinase inhibitor CDKN1B (p27), a Men1 target gene known to be inactivated during prostate cell tumorigenesis, was notably decreased in the prostate cancers that developed in the mutant mice." (PMID 20663219, 2010). "This agrees with reports indicating the high expression of the CDKN1B gene in androgen-dependent prostate cancer cells and a lack of its significance in the case of androgen-independent cells, such as PC-3 cells." (PMID 38067615, 2023). "Finally, we found that the CDKN1B was negatively correlated with FPS and mRNAsi in prostate cancer patients, and subsequent stem cell sphere-forming experiments validated these results." (PMID 36497267, 2022). "Furthermore, SUB1 overexpression elevated PLK1 and C-MYC expression, and reduced CDKN1B expression, showing SUB1 dysregulation triggers alterations in critical oncogenes and tumor suppressors in prostate cancer." (PMID 27270442, 2016). "Inactivation of the tumor-suppressor gene PTEN and lack of CDKN1B expression have been detected in some kinds of cancer, including most advanced prostate cancers and lymphomas." (PMID 27366593, 2015). "Several are known biomarkers for diagnosis and prognosis of prostate cancer (APC, GSTP1, KIT, PYCARD, PGDGRB, RARB, RARRES1, and TIMP1) and some though not biomarkers, were found to be dysregulated in the disease (CDKN1B, MMP7, and MMP9)." (PMID 24626295, 2014). "The mouse models with CDKN1B disruption in combination with other genetic factors, such as Pten and Nkx3.1, have been shown to develop a range of prostate cancers, although CDKN1B inactivation alone displays no obvious neoplastic prostate lesions." (PMID 20663219, 2010). "Similarly, the prediction results for CDKN1B sensitivity (50% inhibitory concentration, IC50) suggested that the CDKN1B high expression group was more sensitive to JQ1_2172 drugs and common chemotherapy drugs for prostate cancer, such as Gemcitabine and Docetaxel." (PMID 36497267, 2022).